PSCA (prostate stem cell antigen)
Diseases named in the same sentence as PSCA in open-access papers (continued):
Sharing a sentence is not in itself a finding about the gene and the disease.
tumor (continued). "Prostate stem cell antigen (PSCA) is such a potential tumor target as it is overexpressed in PCa." (PMID 37298374, 2023). "This is confirmed by the support of the presence of several tumor associated antigens in the prostate; which include the PSA, prostatic acid phosphatase (PAP), prostate specific membrane antigen (PSMA), prostate stem cell antigen (PSCA), mucin-1 (MUC-1), and the cancer testis antigen NY-ESO-1." (PMID 26161414, 2015). "Furthermore, the association between PSCA mRNA expression levels in TCC and different rs2294008 (C>T) genotypes and various clinicopathological features, including tumor stage and grade, were evaluated." (PMID 25624885, 2015). "Copy number increase of HMGA2 and PSCA was detected in one and four tumor, respectively." (PMID 25502777, 2014). "It has been only in the last few years that other immunotherapies have regained interest, not just against PSMA but also anti-PSA, anti-PAP, anti-PSCA, or other more general tumor associated antigens such as B7-H3 or Epithelial Cell Adhesion Molecule (EpCAM) precursor." (PMID 35327339, 2022). "Immunolabeling of key biomarkers, such as prostate-specific membrane antigen (PSMA), prostate stem cell antigen (PSCA), and epithelial–mesenchymal transition (EMT)-related proteins, has demonstrated strong correlations with the tumor grade and stage." (PMID 40801702, 2025). "Additionally, PSCA downregulation may influence the recruitment or polarization of tumor-infiltrating immune cells, contributing to an immunosuppressive microenvironment that favors tumor progression." (PMID 40741413, 2025). "Other proteins, such as prostate stem cell antigen (PSCA) and alpha-methyl acyl-CoA racemase (AMACR), show correlations with the tumor grade and histological subtype." (PMID 40801702, 2025). "Early-phase trials targeting EGFR, MSLN (mesothelin), PSCA (prostate stem cell antigen), and MUC1 have shown preliminary evidence of tumor control, albeit with challenges related to trafficking and the immunosuppressive tumor microenvironment." (PMID 41303058, 2025). "PSCA (Prostate Stem Cell Antigen) is upregulated in SKCM, as suggested by its positive correlation with genes related to RNA modifications, indicating an active role in the tumor’s biological processes." (PMID 41574107, 2025). "For comparative analysis the well characterised prostate stem cell antigen (PSCA)-specific TM was used here, which can effectively redirect UniCAR T cells to tumor cells presenting PSCA32." (PMID 31332252, 2019). "Other prostate cell surface antigens, such as prostate stem cell antigen (PSCA) and six-transmembrane epithelial antigen of the prostate 1 (STEAP1), also exhibit nonspecific expression profiles, potentially leading to similar on-target, off-tumor effects." (PMID 40627156, 2025). "Although some antigens have been discovered that are very tumor selective (e.g., MUC1, EGFRvIII, CEA, GD2 ganglioside, PSCA), essentially no antigens have been discovered that are absolutely restricted to tumor cells." (PMID 31544847, 2019). "Additional reports explored the activity of CAR NK cells in tumor xenograft models, including CAR targets of hematological cancers (e.g., CD19, CD20, CD138, and CS-1) and solid tumors (e.g., HER2, EpCam, GD2, GPA7, PSCA, EGFR, and EGFRvIII)." (PMID 31212634, 2019). "Amongst these genetic factors are polymorphisms at loci encoding cytokines and their receptors, stromal remodelling proteins, such as matrix metalloproteinases, and prostate stem cell antigen (PSCA), which in the context of gastric pathology, acts as a tumour suppressor gene." (PMID 28151409, 2017). "Finally, consistent with tumor regression, prostate stem cell antigen was considerably reduced in TLO and tumor areas from evanescent carcinoma patients." (PMID 28567040, 2017).
tumor (continued). "In another study, CAR containing prostate stem cell antigen (PSCA) scFv fused to DAP12 CAR provided enhanced cytotoxicity of the NK cell line YTS against PSCA-positive tumor cell xenografts and resulted in complete tumor eradication in a significant proportion of treated mice." (PMID 38927974, 2024). "Normal and tumour tissues from such patients were analysed by qRT-PCR for the following 12 genes; six from RNA-seq: CLDN1, MAGEB2, CD24, CEACAM6, IL1B and ISG15 and six from RNA-seq and proteomics cross-linking: AKR1C3, TNFAIP2, RAB7A, LGALS3BP, PSCA and SSRP1." (PMID 36428603, 2022). "Indeed, in preclinical models of pancreatic and prostate cancer, CAR T cells directed against mucin-1 (MUC1) and prostate stem cell antigen (PSCA) were unable to eradicate solid tumors, and tumor escape was attributed to tumor cells expressing low densities of target antigen." (PMID 32357417, 2020).
cancer (48 papers, 2011 to 2025). A tumor composed of atypical neoplastic, often pleomorphic cells that invade other tissues. "Prostate stem cell antigen (PSCA) is associated with disease progression, promotion of angiogenesis, invasion, metastasis and immune evasion in cancer." (PMID 38917176, 2024). "A genome wide association study reported that the T allele of rs2294008 in a cancer-related gene, PSCA, is a risk allele for diffuse-type gastric cancer." (PMID 32664326, 2020). "In recent years, several studies have been widely investigated the possible association between the PSCA polymorphisms and risk of cancer." (PMID 28881685, 2017). "Lastly, increased cancer susceptibility associated with PSCA rs2976392 was also observed in population-based and hospital-based studies." (PMID 28881685, 2017). "Overall, a significant increased risk of cancer was associated with PSCA rs2294008 C>T and rs2976392 G>A polymorphisms." (PMID 28881685, 2017). "Previous studies have investigated the relationships between PSCA rs2294008 C>T and rs2976392 G>A polymorphisms and cancer susceptibility." (PMID 28881685, 2017). "Previous studies have investigated the associations of PSCA polymorphisms with various cancer susceptibility." (PMID 28881685, 2017). "For the PSCA rs2294008 polymorphism, 38 studies were performed on investigating the association between this SNP with susceptibility of cancer, including 34,266 cases and 42,764 controls." (PMID 28881685, 2017). "As a result, we suggested there existed a much stronger advantage to prove the association between PSCA rs2294008 C>T and rs2976392 G>A polymorphisms with the susceptibility to cancer." (PMID 28881685, 2017). "Multiple studies have investigated the association of gene variant of Deleted in colorectal carcinoma (DCC) and Prostate Stem cell antigen (PSCA) with various cancer susceptibility; however, the results are discrepant." (PMID 26891331, 2016). "Recent meta-analysis has revealed the PSCA rs2976392 polymorphism was significantly associated with increased overall cancer risk." (PMID 27050280, 2016). "High expression of PSCA is significantly associated with adverse prognostic features and cancer severity, including; differentiation, invasion, metastasis and decreased overall survival." (PMID 26602921, 2015). "Further, several GWAS and case control studies have demonstrated association of PSCA gene polymorphisms rs2294008 and rs2976392 with various cancers, though some controversies also existed." (PMID 26602921, 2015). "Investigations into the association between PSCA rs2294008 polymorphism and cancer risk have been frequently conducted in either a small or large population to identify the relationship." (PMID 26308216, 2015). "In summary, this meta-analysis suggested that PSCA rs2294008 polymorphism was significantly associated with increased risk of cancer." (PMID 26308216, 2015). "In this work, therefore, with an aim to determine the relationship between PSCA rs2294008 polymorphism and cancer risk and to precisely assess the effect size estimate of the association, we performed a meta-analysis using all available published data." (PMID 26308216, 2015). "Until now, few meta-analysis has been performed to investigate the association of PSCA rs2294008 C>T and rs2976392 G>A polymorphisms with overall cancer risk." (PMID 26124924, 2015). "We searched published literature in Embase and PubMed databases using the search terms “PSCA”, “prostate stem cell antigen”, “variants”, “polymorphism”, “polymorphisms”, and “cancer”." (PMID 26308216, 2015). "Increasing studies have focused on the association of PSCA gene rs2294008 C>T and rs2976392 G>A with cancer risk." (PMID 26124924, 2015). "We found the PSCA rs2294008 C>T polymorphism was associated with overall cancer risk, and the association remained significant among all studies ethnicities and subgroups by source of controls." (PMID 26124924, 2015).
cancer (continued). "To date, although accumulating data have documented the association between PSCA rs2294008 polymorphism and cancer risk, the evidence regarding the role of the polymorphism as a genetic marker for cancer risk remains inconclusive." (PMID 26308216, 2015). "In the present meta-analysis, composed of 27, 197 cancer cases and 48, 237 controls from 21 articles with 24 studies, comprehensively explored the association between PSCA rs2294008 polymorphism and cancer risk." (PMID 26308216, 2015). "By pooling all eligible studies into one large dataset, we found the association between PSCA rs2294008 polymorphism and cancer risk was statistically significant." (PMID 26308216, 2015). "In OSCC cancer, PSCA expression is high in cancerous tissue and may play a role in the development, prognosis and progression of this cancer, and its polymorphisms may also be involved in susceptibility to OSCC, but the molecular mechanism is far from clear." (PMID 38627732, 2024). "PSCA polymorphisms are also involved in the development of this cancer." (PMID 38627732, 2024). "Hence, as we included more studies about the associations between PSCA polymorphisms and the risk of cancer, this meta-analysis was carried out to provide more reliable conclusion to reveal the real associations compared the previous meta-analyses." (PMID 28881685, 2017). "Similarly, for the PSCA rs2976392 polymorphism, there were 18 studies exploring the relationship between this polymorphism and risk of overall cancer with 10,501 cases and 9,766 controls." (PMID 28881685, 2017). "Considering the panoptic role of DCC (rs714) and PSCA (rs2294008, rs2976392) polymorphism in the carcinogenesis, and increasing number of reports on different cancer in recent years, there is a prerequisite to reconcile all the discordant results to clarify its role in cancer susceptibility." (PMID 26891331, 2016). "Consequently, the PSCA rs2294008 C>T polymorphism was significantly associated with increased overall cancer risk." (PMID 26124924, 2015). "The mechanism of PSCA rs2294008 associated with cancer risk remains unclear." (PMID 31416884, 2019). "In this meta-analysis, the results were in concordance with these hypotheses of previous studies, which needed to further prove that PSCA rs2294008 and rs2976392 played an important role in cancer susceptibility as far as possible in all relevant articles published in the future." (PMID 28881685, 2017). "Hence, with this in mind, we conducted the present meta-analysis and TSA to critically evaluate the association between PSCA rs2294008 C>T and rs2976392 G>A polymorphisms and cancer risk and clarify whether the evidence for the results was sufficient." (PMID 28881685, 2017). "Genome-wide association studies have revealed many PSCA polymorphisms, among which rs2294008 C>T, rs2978974 G>A, and rs2976392 G>A are the most widely studied ones and may influence susceptibility to different types of cancer." (PMID 27050280, 2016). "This study identified PSCA as a risk gene (hazard ratio > 1) for BRCA, while FREM1, NPY1R, CCL19 and CLIC6 were the protective genes for the cancer (hazard ratio < 1)." (PMID 39119106, 2024). "CV9103 encodes four specific antigens present in cancer cells: prostate-specific antigen (PSA), prostate-specific membrane antigen (PSMA), prostate stem cell antigen (PSCA), and six-transmembrane epithelial antigen of the prostate (STEAP)." (PMID 36918935, 2023). "In a preclinical murine model of bone mCRPC, γδ CAR-T cells targeting prostate stem cell antigen (PSCA) induced a rapid and significant regression of established tumors, combined with increased survival and reduced cancer-associated bone disease." (PMID 37134157, 2023). "We evaluated this concept in prostate stem cell antigen (PSCA)-positive cancers using the antigen-specific, biotinylated single chain antibody scFv(AM1)-P-BAP conjugated with tetrameric neutravidin." (PMID 29491468, 2018).
cancer (continued). "Kaplan–Meier analysis revealed significant differences in biochemical recurrence, overall survival, and cancer-specific survival according to PSCA mRNA positivity." (PMID 29899859, 2018). "Since SNPs are emerging as promising biomarker of cancer susceptibility, here, we aimed to execute a meta-analysis of DCC (rs714 A > G) and PSCA (rs2294008 C > T, rs2976392 G > A) polymorphism to demonstrate the more accurate strength of these associations." (PMID 26891331, 2016). "In addition to PSCA dysregulation, its very common polymorphism rs2294008 is also involved in the development of OSCC cancer." (PMID 38627732, 2024). "A prevailing view holds that some GPI-APs, such as PSCA, the urokinase receptor (u-PAR), C4.4A, and MMPs, are deeply involved in cancer invasion and metastasis." (PMID 31118109, 2019). "Some cancer-related genes are located in these highly common, early appearing RARs: MCL1, CTSK, ARNT, S100A10, PTK2, PTP4A3, and PSCA in the RAR-Gs; and DLC1, PINX1, and GATA4 in the RAR-Ls." (PMID 22938721, 2012). "Data from IHC analysis indicated that the PSCA protein is not present in the epithelium of normal lung tissue but is found in its cancer counterpart and is localized in the cytoplasm of lung tumor cells." (PMID 38627732, 2024). "Besides CD133, prostate stem cell antigen (PSCA), CD90, EpCAM, and ALDH also can be considered as important target antigens for CAR-T-cell therapy in cancer treatment, which needs further study in both preclinical and clinical settings." (PMID 33968014, 2021). "Accordingly, in the present study, we investigated whether the detection of PSCA mRNA in the blood prior to operation may have predictive value for BCR, overall survival (OS), and cancer-specific survival (CSS) after RP with in patients with high-risk PC in a long-term follow-up study." (PMID 29899859, 2018). "Additionally, the prostate stem cell antigen (PSCA), overexpressed in a range of malignancies including mCRPC, is the target of GEM3PSCA, an affinity-tailored T cell adaptor that is currently being evaluated in a phase 1 clinical trial (NCT03927573) for PSCA-positive cancer." (PMID 37762648, 2023). "Moreover, the expression of PSCA in esophagus was negative in both normal and cancer tissues." (PMID 26006239, 2015).
adenocarcinoma (2 papers, 2013 to 2023). A common cancer characterized by the presence of malignant glandular cells. "We found that 54.6% of adenocarcinoma exhibited overexpression of PSCA and 55.6% of adenocarcinoma exhibited a significantly elevated Oct-4 level." (PMID 23984394, 2013).
bacterial diseases (2 papers, 2017 to 2019). "We show here that saturating PsPto-PscA with d-Asp reduced bacterial infection, which is most likely due to a reduction in chemotaxis toward plant openings." (PMID 31575767, 2019). "As NRP1 was required for defense responses against cold stress and avirulent bacteria, this suggests that NRP1 may play a role in PsCA-induced defense against chilling and bacterial diseases." (PMID 29403505, 2017).
PSCA also shares sentences with these, for which no sentence is quoted: cardia (4 papers); glioblastoma (3); renal cell carcinoma (3); infection (2); ovarian carcinoma (2); ovarian mucinous tumor (2); Peptic ulcer (2); prostate (2); B cell lymphoma (1); cardia stomach cancer (1); colon cancer (1); diabetic nephropathy (1); esophageal cancer (1); Familial adenomatous polyposis (1); fibrosarcoma (1); head neck carcinoma (1); melanoma (1); metastatic disease (1); metastatic prostate carcinoma (1); multiple myeloma (1); neuroblastoma (1); polyp (1); skin cutaneous melanoma (1); small lymphocytic lymphoma (1); thyroid cancer (1); urothelial carcinoma (1).